ENSG00000235007 (novel protein)
Gene: Protein-coding gene on chromosome 9 (129,139,413 to 129,260,575, forward strand). Ensembl gene ENSG00000235007.
Genetic constraint (gnomAD): Loss-of-function variants: 2 observed, 3.72 expected, observed/expected ratio (o/e) 0.54, 90% interval 0.22 to 1.57. That is too few expected variants to judge how well the gene tolerates losing a copy. Missense variants: 35 observed, 48.78 expected, observed/expected ratio (o/e) 0.72, 90% interval 0.55 to 0.95. Synonymous variants: 15 observed, 17.82 expected, observed/expected ratio (o/e) 0.84, 90% interval 0.56 to 1.3.